IL10 (interleukin 10)
Diseases named in the same sentence as IL10 in open-access papers (continued):
Sharing a sentence is not in itself a finding about the gene and the disease.
infection (continued). "Additionally, at these intervals of infection we observed a slight increase in necrotic tissues in IL-10 KO compared to wild-type livers which was not statistically significant." (PMID 24069337, 2013). "It has been demonstrated previously that during L. major infections high local Arginase-1 levels at the site of infection mediate L-arginine depletion, which results in impaired local CD4+ (and CD8+) T cell function, particularly IFN-γ production but also to a lesser extent IL-4 and IL-10." (PMID 23437409, 2013). "Likewise, even though high percentages of NK cells produced IL-10 early after infection, NK cell specific IL-10 knockout mice were not able to clear LCMV and exhibited exhausted T cells." (PMID 24244162, 2013). "Although the absence of IL-10 leads to a better clearance of some pathogens with no enhanced immunopathology, during other infections lack of IL-10 can be accompanied by an immunopathology that is detrimental to the host but does not necessarily affect the pathogen load." (PMID 24069337, 2013). "Based on the finding that CD4+ and CD8+ T cells produced IL-10 after Clone 13 infection and that CD4+ T cell depletion decreased IL-10 mRNA levels on day 5 post infection, we investigated if T cell derived IL-10 complements macrophage derived IL-10 to exert it's biological effects." (PMID 24244162, 2013). "Significantly less induction of pro-inflammatory cytokines, TNF-α, IL-6, IL-1β and MCP-1, was found at various time post-infection in ApoE−/− mice; whereas anti-inflammatory cytokine IL-10 was not affected, and IL-12 production was not detectable during infection." (PMID 23977160, 2013). "Expression levels of interleukin (IL)-4, IL-10, IL-13 and tumor necrosis factor (TNF)-α were significantly up-regulated while interferon (IFN)-α, IFN-β, IFN-γ, IL-1β,IL-2, IL-3, IL-15, IL-17F, IL-18 and colony-stimulating factor (CSF)-1 were markedly decreased in PBMCs at all stages of infection." (PMID 24358317, 2013). "Finally, IL-10, a suppressive cytokine, which was not present early on, was upregulated on days 28 and 35 post infection, perhaps as a repair mechanism following the acute inflammation." (PMID 24204830, 2013). "However, cell type composition did not significantly differ between the IL-10 mutant strains nor change during the first week of infection." (PMID 23825956, 2013). "Infection with H. hepaticus alone is not sufficient to induce IBD in Il10−/− mice." (PMID 23951007, 2013). "Here, we demonstrate that T cell responses improved markedly, and that normally chronic LCMV Clone 13 infection could be cleared when either myeloid cells or T cells lacked IL-10 production." (PMID 24244162, 2013). "However, unlike LPS-positive Gram-negative bacteria, severe infection with LPS-negative Ehrlichia induced a concomitant upregulation of both pro-inflammatory cytokine genes and key anti-inflammatory genes, such as il-10 and il-1ra." (PMID 23526993, 2013). "In fact anti-GIPL IgG1 levels measured at earlier times predict higher parasite loads later in infection, suggesting that the anti-GIPL antibodies may induce higher parasite loads through IL-10, rather than merely being caused by the higher parasite burdens." (PMID 23675550, 2013). "In the ‘typical’ generalized infection with O. volvulus, immunosuppression of Th1 and Th2 responses is thought to occur via a specific T regulatory-1 response and the non-specific involvement of IL-10." (PMID 22479660, 2012). "While enhanced immune responses and viral eradication achieved in the absence of IL-10 may be desirable outcomes, the absence of IL-10 may promote unwanted immune mediated pathology with or without improved viral elimination depending on the site of infection." (PMID 22880122, 2012). "Indeed IL-10 and TGF-β provide a suppressive milieu in the site of Leishmania infection, which promotes parasite persistent and replication, as well as prevention of excessive immunopathology in different stages of infection." (PMID 23109946, 2012).
infection (continued). "Using IL-10 green fluorescence protein (GFP) reporter knock-in mice, designated IL-10-internal ribosomal entry site (IRES)-GFP-enhanced reporter (tiger), NK cells are identified as major IL-10 expressing cells in the liver after infection, along with T cells and other leukocytes." (PMID 22880122, 2012). "In the absence of IL-10, mice exhibit marked elevations in proinflammatory cytokines and in the numbers of mononuclear cells and lymphocytes infiltrating the liver during this infection." (PMID 22880122, 2012). "The induction of the M2b phenotype, correlating with higher IL10 levels and a Th2-type response, was dependent on TLR4 and NE activities, suggesting that the engagement of TLR4 might be beneficial to the parasite at later stages of infection." (PMID 22523644, 2012). "Furthermore, while the kinetics of CXCL9 production were similar between WT and IL-10−/− mice on days 4 and 5 post infection, CXCL9 levels produced by IL-10−/− leukocytes were greater 7 days post infection as compared to levels measured in WT leukocyte conditioned media." (PMID 22880122, 2012). "In contrast, no significant IL-10 expression was noted following 5 h of infection with rPVL." (PMID 22529963, 2012). "Levels of IL-4, IL-10 and IFN-γ from splenocytes were elevated in all infected animals compared to uninfected MBP-vaccinated animals when restimulated ex vivo with SEA and SWAP, indicating that infection-related cytokine responses were produced, although responses to SEA were generally higher." (PMID 22428079, 2012). "Given the increased total leukocyte infiltration in the absence of IL-10 during this infection, we investigated whether this rise in cell number was due to elevations in the numbers of a few or all of these effector cell populations." (PMID 22880122, 2012). "We later showed that immunization with L. intermedia SGS altered the course of experimental infection with L. braziliensis and stimulation of immune mice with a combination of SGS and L. braziliensis led to a decreased CXCL10 expression and increased IL-10 expression." (PMID 23284976, 2012). "It has been suggested that signaling downstream of CD40 may perpetuate IL-10 production and enhance productive infection of macrophages but this has not been evaluated in DCs." (PMID 22911108, 2012). "Moreover, P3 infection significantly enhanced the release of CCL2 and IL-10." (PMID 21269456, 2011). "Moreover, this infection induces an enhanced expression of soluble pro-inflammatory factors, including TNF-α and the active gMMP-9, as well as a decreased expression of anti-inflammatory cytokines, such as IL-10 and TGF-β." (PMID 21569520, 2011). "In addition, P3 infection suppressed the expression of interferon (IFN)-α and tumor necrosis factor (TNF)-α but enhanced the production of chemokine (C-C motif) ligand 2 (CCL2) and interleukin (IL)-10 of DCs." (PMID 21269456, 2011). "We showed that innate TNF-α responses and TNF-α: IL-10 ratios upon TLR2 stimulation of PBMCs were significantly higher in S. haematobium-infected children compared with those without infection, in the face of enhanced regulatory adaptive responses to schistosomal antigens." (PMID 21931706, 2011). "We could not detect any significant production of IL-10 or IL-12p70 after co-culturing with ApoAct, regardless of infection status (data not shown)." (PMID 21698207, 2011). "Moreover, the injection of CFA did not affect the course of infection in IL-4-deficient mice, suggesting the exacerbation of PCM after inoculation of CFA was mediated by IL-4 and not IL-10." (PMID 21731741, 2011). "Indeed, no increase in the number of cells producing IL-10 above that in naïve resulted from infection with SGB1 Vi−." (PMID 21829346, 2011).
infection (continued). "Also, CXCL-10 is specific for effector T-cell recruitment during infection and, therefore, its deletion reduces T-cell trafficking, which enhances production of CD4+CD25+Foxp3+ and suppressive cytokines interleukin-10 (IL-10) and tumor growth factor- β1 (TGF-β1)." (PMID 21439091, 2011). "Notably, the expression of IFN-γ and IL-10 were not different between naïve WT and IL-13−/− mice and the onset of IFN-γ and IL-10 production was not affected by the absence of IL-13 during the early stages of infection." (PMID 21573182, 2011). "Moreover, the granzyme b, nk-lysin, ifnγ, il4 and il10 mRNA levels in early skin-draining lymph nodes of immunized pigs were higher than those in pigs with non-irradiated cercariae infection." (PMID 20976218, 2010). "It is noteworthy that IL-10 levels were maintained close to the basal level among infected animals on the 7th and 21st days p.i., while pro-inflammatory cytokine levels (TNF-α, CCL2, IL-6 and IFN-γ) presented a great variation among different experimental groups during the acute phase of infection." (PMID 20967289, 2010). "Further, infection alters TLR responsiveness, as IL-12 production (as measured by ex vivo intracellular staining of CD11c+ DCs) in response to LPS stimulation is reduced, while IL-6, TNF-α and in particular, IL-10 all increase following infection with either nematode parasite." (PMID 19766674, 2009). "Levels of sTNF-RII (P = 0·008), IL-10 (P = 0·011) and IL-5 (P = 0·025) were also significantly higher in children with S. mansoniinfection without P. falciparuminfections, compared with children with neither infection." (PMID 19149774, 2009). "Post hoc analysis indicated that levels of sTNF-RII (P = 0·005), IL-10 (P = 0·020), IL-5 (P = 0·027) were significantly higher among children who were co-infected with S. mansoniand P. falciparum, compared with levels among children who had neither infection." (PMID 19149774, 2009). "Our studies therefore suggest that while IFN γ may play an important role in resolution of infection and TST conversion, IL-10 may be critical in dampening the pro inflammatory arm of the immune response as well as in initiation of dormancy during the later phase of infection." (PMID 19826490, 2009). "The regulatory cytokine IL-10 could not be detected directly ex vivo as it was below detection limit both 2 and 4 weeks post infection (detection limit: 0·37%, data not shown)." (PMID 19292771, 2009). "In contrast to recent studies describing a role for IL-10 producing Th1 cells in Toxoplasma gondii and Leishmania spp infections, the adaptive IL-10 producing Tregs we describe do not co-express IFN-γ or other effector cytokines and better fit the definition of Tr1 cells." (PMID 18401464, 2008). "Moreover, splenocytes from susceptible BALB/c mice, but not resistant DBA/2 mice, infected with PyNL produce IL-10 and TGF-beta during the early acute stage of infection, which is associated with an increase in the proportion of splenic CD25+ CD4 T cells." (PMID 18401464, 2008). "Furthermore, approx 30% (6/21 mice) of IL-10−/− (but not WT) mice infected with 104 PyL pRBC were able to control their infections and survived, with parasitaemia declining from a peak of approx 45% on day 6pi." (PMID 18401464, 2008). "This is particularly interesting because the role of IL-10 in TB is controversial, since it has been reported that IL-10-/- mice are not protected from infection while others showed that increases of IL-10 expression leads to a down regulation of the immune response against TB." (PMID 18647414, 2008). "The enhanced levels of IL-10 may not be acting as anti-inflammatory mediator and might be involved in prolonging the infection by exerting immunostimulatory effects." (PMID 18489796, 2008).
infection (continued). "In confirmation of this, by day 7 post-infection, IL-10+ CD4+ T cells were almost exclusively CD25− indicating that, since the majority of Foxp3+ cells maintain CD25 expression during P. yoelii infection, CD25−Foxp3− CD4+ T cells are the primary source of IL-10 during both PyL and PyNL infection." (PMID 18401464, 2008). "Absence of IL-10 in the early phase of infection favors increased resistance to mycobacteria." (PMID 17714584, 2007). "Notably, neither infection nor ouabain treatment significantly altered IL-10 levels." (PMID 40895521, 2025). "Additionally, PGD2 upregulated both IL-6 and IL-10, regardless of the infection stage." (PMID 40874199, 2025). "However, ZNFX1 did not appear to affect IL-4 and IL-10 expression in the early stages of infection." (PMID 38016036, 2024). "Later, as a mechanism to combat infection and regulate pro-inflammatory cytokine, Leishmania may modulate host machinery to activate SHP-1, a phosphatase, and to inactivate NFAT5, and therefore the chromatin architecture changes entirely, which activates the IL-10 gene." (PMID 38299832, 2024). "Interestingly, only mice born to L.rh supplemented mothers further displayed an increased activation of IFN-γ producing virtual memory CD8 T cells and a production of IL-10 by CD4 and CD8 T cells that could explain a better control of the lung damages upon infection." (PMID 39710590, 2024). "Interestingly, the current study shows that the frequencies of IL-10+ PMN-MDSCs were highest in the patent W. bancrofti-infected, indicating that MDSCs are critical for the induction of regulatory immune responses, which is a characteristic of patent W. bancrofti-infections." (PMID 37242335, 2023). "However, it has not been reported whether the aquatic animal infection virus can upregulate the expression of host IL-10 and the mechanisms are still unknown." (PMID 38004823, 2023). "In addition, depending on the condition, cytokines such as IL-10 could have been produced by other non-inflammatory cells so that a huge proportion of the children had detectable levels regardless of infection status." (PMID 37018184, 2023). "Notably, lower levels of IL-10 were observed in the humanized mice, suggesting that HLA-A11/DR1 may extend the presence of pro-inflammatory factors and interfere with IL-10 secretion during infection." (PMID 38035330, 2023). "However, it had not been clear which cells supply IL-10 in the BM after infection." (PMID 36719648, 2023). "However, the depletion of Treg cells prior to infection did not significantly impact the development of total IgG production against B. burgdorferi but did result in an eventual increase in the levels of serum IL-10." (PMID 36839461, 2023). "Blockade of IL-10 resolved chronic viral infection and T cell exhaustion in some settings, suggesting that Tox-mediated IL-10 production may play a negative role in resolving infection." (PMID 38054003, 2023). "No significant levels of IL-10 were detected in Att-S74-T3Bo-infected and control animals after Vir-S74-T3Bo infection, except for an increase of this cytokine in control calves at 13 days post-infection, at the time two control animals were euthanized due to the severity of acute disease." (PMID 36466866, 2022). "Depending on the trypanosome species and the stage of infection, different cellular sources could contribute to IL-10 production such as NK cells, CD8+ T cells and CD4+ T cells around peak parasitaemia as well as B cells and plasma cells, myeloid cells and hepatocytes as the infection progresses." (PMID 35464430, 2022). "Furthermore, the induction of IL10 and of SOD1 gene expression was also dependent on TLR3, showing that the anti-viral-type responses conveyed via PKR and TLR3 are mobilized by L. donovani to downmodulate the inflammatory response of macrophages, likely influencing infection." (PMID 35154115, 2022).
infection (continued). "As there is evidence for increased IL-4 and IL-10 responses in the airways of RSV-infected patients, the reduced blood transcriptomic markers could be due to a local response to RSV, but with limited evidence for immune cell signalling in the airways during infection, this is still unknown." (PMID 35406717, 2022). "Altogether, these data demonstrate that the onset of the BCG-specific CD4+ T-cell response is similar in both B6- and pMT-10-vaccinated mice, thus supporting the hypothesis that IL-10 overexpression during infection does not significantly impair BCG-mediated immunity." (PMID 35935958, 2022). "Meanwhile, anti-inflammatory factors such as TNFAIP3, NFKBIA, NFKBIZ, SOCS1, SOCS3, and IL-10 were elevated, with the reverse trends for the inflammation-inducing genes PPBP and MARCO at 38 hpi, suggesting that the pro- and anti-inflammatory responses might coexist in PAMs during YC-2020 infection." (PMID 36338035, 2022). "It meant that USA300 infection may not affect the expression of IL‐4 and IL‐10 in the mPFC." (PMID 35977050, 2022). "In particular, immunosuppressive IL-10 secretion by NK cells has been described to occur in systemic, but not local, infections as a recent immunoregulatory mechanism of inflammation that may be detrimental or beneficial, depending on the timing of release, type of disease, or the infection model." (PMID 35053151, 2021). "For our study, it could be hypothesized that if GG is the genotype with low IL10 production, then the lack of suppression (especially of interferon-γ) will upregulate the host defense against intracellular infections, clearing the infection at an early stage." (PMID 33430411, 2021). "Remarkably, we found higher TNF, IL-1β, IL-6, and IL-10 in lung homogenates of LysM-cre × Hif1αfl/fl mice when compared with Hif1αfl/fl control mice at 12 hours after inoculation, but these differences in pulmonary cytokine levels were not present after 40 hours of infection." (PMID 34393650, 2021). "No raise in IFN-γ expression was observed after heterologous infection as well as no clear change in expression for other tested cytokines could be observed, except for an approximately 5-fold increase in TNFα, IL-10 and TGF-β mRNA in some genotype B strain infected goats." (PMID 34575988, 2021). "Thus, our data suggest that while IL-10 does not contribute to the reduced antigen-experienced CD8 T cell response to ZIKVBR infection, this defect may be due to a reduced IFN-I response." (PMID 34193875, 2021). "Moreover, cervico-vaginal lavages (CVL) of HIV infected women sampled within weeks of infection had significantly elevated levels of IL-6, IL-10, and IL-12, compared to HIV negative women whereas, IL-1α, IL-1β, IL-8, IL-6, IP10 and IL-10 were increased in plasma of the same patients." (PMID 32615983, 2020). "Although there were no typical symptoms after infection, the expression of proinflammatory cytokines IL-1β, IL-6 and IL-8 were significantly induced at 5 dpi in lungs and at 7 dpi in spleen, and at the same time, the expression of anti-inflammatory cytokine IL-10 was also induced." (PMID 31992193, 2020). "In addition, our work showed that there was a significant increase in the expression of the anti-inflammatory cytokine IL-10, which occurred on the last day of the infection and perhaps because of this fact, it was not effective in reducing the inflammatory response." (PMID 32294697, 2020). "IL-10 was also found to be present at high levels in the supernatants of splenocyte cultures from the immunized mice, but these were significantly lower after the challenge infection, and were not different from the control groups; again at the limit of detection." (PMID 32916868, 2020). "However, this IL-10 response was selectively suppressed upon exposure to sEVs from poly(I:C) (dsRNA) treated vaginal cells as well as vaginal sEVs from the TVV+TV but not the TVV-TV infection." (PMID 33224901, 2020).